FASLG (Fas ligand)
Description:
Cytokine that binds to TNFRSF6/FAS, a receptor that transduces the apoptotic signal into cells. Involved in cytotoxic T-cell-mediated apoptosis, natural killer cell-mediated apoptosis and in T-cell development. Initiates fratricidal/suicidal activation-induced cell death (AICD) in antigen-activated T-cells contributing to the termination of immune responses (By similarity). TNFRSF6/FAS-mediated apoptosis also has a role in the induction of peripheral tolerance (By similarity). Binds to TNFRSF6B/DcR3, a decoy receptor that blocks apoptosis. [Tumor necrosis factor ligand superfamily member 6, soluble form]: Induces FAS-mediated activation of NF-kappa-B, initiating non-apoptotic signaling pathways (By similarity). Can induce apoptosis but does not appear to be essential for this process. [FasL intracellular domain]: Cytoplasmic form induces gene transcription inhibition.
Synonyms: APTL; CD95-L; FasL; CD178; APT1LG1; CD95L; TNFSF6; ALPS1B; TNLG1A
Tractability: Antibody: UniProt places it where antibodies can reach, with high confidence; its Gene Ontology location is reachable by antibodies, with high confidence; UniProt predicts a signal peptide or a membrane-spanning region. PROTAC: UniProt records ubiquitination sites on it. Other modalities: a drug acting on it is in phase 2 or 3 trials.
Target class: Secreted protein
Gene: Protein-coding gene on chromosome 1 (172,659,102 to 172,666,876, forward strand). Ensembl gene ENSG00000117560.
Subcellular location: Cell membrane; Cytoplasmic vesicle lumen; Lysosome lumen; Secreted (Tumor necrosis factor ligand superfamily member 6, soluble form); Nucleus (FasL intracellular domain)
Pathways (Reactome):
Programmed Cell Death: CASP8 activity is inhibited; Caspase activation via Death Receptors in the presence of ligand; Dimerization of procaspase-8; RIPK1-mediated regulated necrosis; Regulation by c-FLIP
Immune System: Interleukin-4 and Interleukin-13 signaling; TNFs bind their physiological receptors
Disease: Deregulated CDK5 triggers multiple neurodegenerative pathways in Alzheimer's disease models
Gene expression (Transcription): FOXO-mediated transcription of cell death genes
Signal Transduction: FasL/ CD95L signaling
Gene Ontology:
Molecular function: cytokine activity; protein binding; signaling receptor binding; death receptor binding; tumor necrosis factor receptor binding
Biological process: apoptotic signaling pathway; extrinsic apoptotic signaling pathway; extrinsic apoptotic signaling pathway via death domain receptors; necroptotic process; necroptotic signaling pathway; negative regulation of angiogenesis; negative regulation of transcription by RNA polymerase II; positive regulation of apoptotic process; positive regulation of canonical NF-kappaB signal transduction; positive regulation of endothelial cell apoptotic process; positive regulation of phosphatidylserine exposure on apoptotic cell surface; release of sequestered calcium ion into cytosol by endoplasmic reticulum; T cell apoptotic process; apoptotic process; cell-cell signaling; positive regulation of extrinsic apoptotic signaling pathway; signal transduction; cell communication; cellular response to type II interferon; endosomal lumen acidification; immune response; inflammatory cell apoptotic process; intracellular chloride ion homeostasis; positive regulation of cell population proliferation; positive regulation of epidermal growth factor receptor signaling pathway; and 4 more
Cellular component: extracellular exosome; extracellular region; nucleus; plasma membrane; caveola; cell surface; cytoplasm; cytoplasmic vesicle lumen; external side of plasma membrane; lysosomal lumen; membrane; perinuclear region of cytoplasm
Genetic constraint (gnomAD): Loss-of-function variants: 9 observed, 25.91 expected, observed/expected ratio (o/e) 0.35, 90% interval 0.21 to 0.61. The upper end of that interval is the gene's LOEUF score, 0.61, which puts it in group 2 of 6, group 1 being the genes least tolerant of losing a copy. Missense variants: 306 observed, 363.67 expected, observed/expected ratio (o/e) 0.84, 90% interval 0.77 to 0.93. Synonymous variants: 130 observed, 142.8 expected, observed/expected ratio (o/e) 0.91, 90% interval 0.79 to 1.05.
Gene-disease validity (ClinGen):
ClinGen rates the evidence that FASLG causes each of these diseases.
autoimmune lymphoproliferative syndrome type 1 (autosomal recessive): Definitive.
Homologues: Orthologues: chimpanzee FASLG (99% identical), macaque FASLG (98% identical), dog FASLG (88% identical), pig FASLG (85% identical), mouse Fasl (77% identical), rabbit FASLG (76% identical), rat Faslg (75% identical), tropical clawed frog faslg (41% identical), zebrafish faslg (27% identical). Paralogues in human: TNFSF15 (24% identical), TNFSF14 (20% identical), TNF (19% identical), LTA (18% identical), LTB (18% identical), TNFSF10 (18% identical), CD40LG (16% identical), TNFSF11 (15% identical).
Diseases named in the same sentence as FASLG in open-access papers:
FASLG is named in the same sentence as 538 diseases in open-access papers, as found by Europe PMC text mining. Sharing a sentence is not in itself a finding about the gene and the disease. The quoted sentences say what the papers report.
thrombosis (187 papers, 2004 to 2026). "In addition, we confirmed that miR-21 regulated function of EPCs via targeting FASLG, thus upregulation of miR-21 expression leading to increased thrombus resolution in a murine model of venous thrombosis." (PMID 31416448, 2019).
systemic lupus erythematosus (109 papers, 2004 to 2026). An autoimmune multi-organ disease typically associated with vasculopathy and autoantibody production. "Besides its physiological role (of inducing apoptosis), the Fas–Fas ligand (FasL) pathway was implicated in autoimmune diseases with diverse background, such as systemic lupus erythematosus (SLE) and multiple sclerosis." (PMID 37353767, 2023). "An earlier study has reported that EGR2 was upregulated in the DNT cells of MRL-lpr (Faslpr mutation) and C3H-gld/gld (Faslgld mutation) lupus mice and bind to Fas ligand regulatory element (FLRE) to upregulate expression of Fas ligand (FasL)." (PMID 32646370, 2020). "Lupus is a chronic inflammatory autoimmune disease influenced by multiple genetic loci including Fas Ligand (FasL) and P2X7 receptor (P2X7R)." (PMID 23284917, 2012). "Over-expression of membrane-bound Fas ligand (CD95L) exacerbated autoimmune disease and renal pathology in pristane-induced lupus, and administering anti-FasL monoclonal antibody to an NZB/W F1 mouse model of lupus prevented the development of lupus nephritis." (PMID 26076826, 2015). "Levels of inflammatory cytokines have been found to be altered in gld.apoE−/− mice (mice with lupus-like features and atherosclerosis, which have absent functional Fas ligand and apolipoprotein E) treated with statins." (PMID 30959892, 2019).
breast carcinoma (99 papers, 2000 to 2025). "FASLG encodes Fas ligand, which induces apoptosis upon binding to Fas, and polymorphisms in which contribute to breast cancer risk." (PMID 27846853, 2016). "To recapitulate, we proposed a hypothesis that lncRNA CASC7 is associated with the breast cancer development by regulating miR-21-5p/FASLG axis." (PMID 34889164, 2021). "In addition, breast cancer has always considered as a cold tumor, the loss of tumor antigens, expression of Fas ligand (FasL) and programmed cell death 1 ligand, and production of immunosuppressive cytokines such as TGF-beta and IL-10 are some of the mechanisms of immune escape." (PMID 34631507, 2021). "In the case of extrinsic pathway, the appearance of fas ligand (fasL) is proved to be directly reduced by the miR-21 in the breast cancer cell line to promote the apoptotic event." (PMID 38726321, 2024). "In breast cancer, lncRNA cancer susceptibility candidate 7 (CASC7) upregulated levels of tumor necrosis factor ligand superfamily member 6 (FASLG) by targeting miR-21-5p to inhibit proliferation, invasion, and migration of cancer cells." (PMID 35030969, 2022). "Except for the five genes ITPK1, RIPK3, STAT3, TNF, and FASLG, the remaining 62 genes showed significant differences in expression between breast cancer and normal breast samples." (PMID 36675706, 2022). "For this reason, lots of researchers intend to activate the FAS/FASLG signaling for breast cancer treatment." (PMID 34889164, 2021). "As a consequence, we confirmed that lncRNA CASC7 regulates miR-21-5p/FASLG axis to suppress the development of breast cancer." (PMID 34889164, 2021). "To make clear how lncRNA CASC7 exerts its function in breast cancer, we subsequently performed rescue experiments to illustrate that lncRNA CASC7 suppresses to malignant behaviors of breast cancer by regulating miR-21-5p/FASLG pathway." (PMID 34889164, 2021). "As immune cells, including natural killer (NK) cells and T cells, produce Fas-ligand, our data suggest that LIV renders breast cancer cells more susceptible to immune-mediated apoptosis." (PMID 33298883, 2020). "It has been reported that lncRNA MAGI2-AS3 regulated breast cancer cell proliferation through the modulation of Fas and Fas ligand." (PMID 31832086, 2019). "In a recent study, it has been reported that lncRNA MAGI2-AS3 regulated breast cancer cell proliferation through the modulation of Fas and Fas ligand." (PMID 31832086, 2019). "In breast cancer, Fas-ligand-positive breast cancer cells induce the apoptosis of Fas-positive activated lymphocytes, which also results in immune escape." (PMID 29041905, 2017). "Interestingly, previous studies have demonstrated that EREs are present in the promoters of Fas ligand (FasL) and that estrogens promote FasL expression in ER+ breast cancers." (PMID 39682229, 2024). "Moreover, it was reported that CASC7 suppresses malignant behaviors of breast cancer by regulating the miR-21-5p/FASLG axis." (PMID 35484972, 2022). "Notably, our results suggested that lncRNA CASC7 plays its anti-cancer effect to inhibit miR-21-5p level, eventually amplifying the FASLG level in breast cancer." (PMID 34889164, 2021). "However, these interactions between lncRNA CASC7 and miR-21-5p or miR-21-5p and FASLG are still indefinite in breast cancer." (PMID 34889164, 2021). "Finally, we validated that lncRNA CASC7 suppresses malignant behaviors of breast cancer by regulating the miR-21-5p/FASLG axis." (PMID 34889164, 2021). "Furthermore, we validated that LncRNA CASC7 suppressed to malignant behaviors of breast cancer by modulating miR-21-5p/FASLG axis." (PMID 34889164, 2021). "Thus, our data indicated that both the miR-21-5p and CASC7 could regulate FASLG expression in breast cancer cells." (PMID 34889164, 2021).
breast carcinoma (continued). "The somewhat surprising association of the PC1 with Fas-ligand expression on cytotoxic T-cells may support the earlier notion of a mixed signature of activation and suppression in T-cells from early-stage breast cancer patients." (PMID 24237611, 2013). "The interaction between FASLG and FAS activates RIPK1, leading to necrosome formation that trigger necroptosis in tumor cells, potentially indicating breast cancer." (PMID 38460046, 2024). "In breast tumor tissues from n=88 patients with basal breast cancer, CXCL1 and FASLG expression were found to increase significantly as the MDSC expression score increased." (PMID 33123173, 2020). "While not abundant in cancer cells, CXCR1 was identified on breast cancer stem-like cells (CSCs) where it plays a major role in regulating the breast CSCs and surrounding cancer cell survival via Fas-ligand mediated pathways." (PMID 35754051, 2022). "We report that obesity increases CXCL1 concentrations in the mammary tumor microenvironment, driving CXCR2-mediated chemotaxis and accumulation of granulocytic myeloid-derived suppressor cells (G-MDSCs) expressing Fas ligand (FasL)." (PMID 33123173, 2020). "We identified two genes with a significant gain in correlation with PTEN in breast cancer samples with PTEN mutations (n = 27) compared to samples without PTEN mutations (n = 816), FASLG and IPCEF1." (PMID 27846853, 2016). "This cell line is highly aggressive and does not undergo to apoptosis via Fas-ligand upon paclitaxel challenge (data not shown), as described for other breast cancer cell lines." (PMID 26517518, 2015). "In breast cancer cell line MCF-7 and HeLa cells, PEA-15 overexpression inhibits Fas ligand (FasL) and Fas/TNFα apoptotic effects by blocking the interaction between FADD and caspase-8, preventing the recruitment and activation of caspase-8 at the death-inducing signaling complex (DISC)." (PMID 26263999, 2015). "The role of necroptosis-related genes in breast cancer, such as FASLG, FLT3, HSPA4, IDH2, IPMK, LEF1, and SLC39A7, has not been extensively studied, and these necroptosis-related genes have been confirmed to regulate the biological processes of necroptosis in various types of tumors." (PMID 36675706, 2022). "The expression of Fas and PTEN have previously been found to be negatively correlated in prostate cancer, consistent with the negative correlation we identify between PTEN and FASLG in the PTEN wildtype breast cancer samples, suggestive of negative regulation at baseline." (PMID 27846853, 2016). "Furthermore, in several breast cancer cell lines, RGZ activated the human Fas ligand (FasL) promoter in a PPARγ-dependent manner, increased the binding of PPARγ with Sp1 to the Sp1 sequence located within the FasL promoter, and positively regulated FasL expression." (PMID 36611922, 2022). "Our study further found that ABL-N induced significant activation of caspase-8 in the breast cancer cells, suggesting that ABL-N may activate the death receptor pathway and induce the expression of death receptors or death ligands such as tumor necrosis factor-α and Fas ligand." (PMID 20096139, 2010).
autoimmune disease (97 papers, 2006 to 2026). A disorder resulting from loss of function or tissue destruction of an organ or multiple organs, arising from humoral or cellular immune responses of the individual to their own tissue constituents. "The abnormal expression of Fas cell surface death receptor (FAS) and Fas ligand FASLG has been shown to be associated with some autoimmune diseases." (PMID 36466094, 2022). "Apoptosis is essential to the maintenance of self-tolerance, thus mutations in apoptosis regulating genes such as Fas and Fas ligand (FasL) in humans as well as in mouse models have been implicated in autoimmune diseases." (PMID 33717145, 2021). "As MRL/lpr mice, MRL/gld mice are deficient in a functional Fas ligand and spontaneously develop autoimmune diseases involving both lethal glomerulonephritis and systemic arteritis." (PMID 30429537, 2018). "Additionally, a member of FAS ligand’s family FASLG (FASLG fold change = 5.53) has also been implicated in the progression of several autoimmune diseases (such as SLE, ALPS (autoimmune lymphoproliferative syndrome) and immunodeficiency with autoinflammation)." (PMID 40149697, 2025). "Fas can induce T-cell apoptosis by binding to the Fas Ligand (FasL), so decreased gene Fas expression may lead to the accumulation of activated T-cells and cause autoimmune diseases." (PMID 36362342, 2022). "AA is an autoimmune disease caused by T cells attacking hair follicles expressing FAS and its ligand (FASLG) on the perifollicular infiltrates." (PMID 39459398, 2024). "Specifically, lymphoproliferative syndrome illustrates the role of cell death in autoimmune diseases with natural mutants such as a homozygous null FAS ligand (FASLG) leading to uncontrolled proliferation of lymphocytes accompanied by autoimmune cytopenia." (PMID 33193409, 2020). "They observed that mainly Fas ligand (FasL) contributes in the pathogenesis of autoimmune diseases." (PMID 30429845, 2018). "The Fas / Fas ligand - cell death mechanism has a significant role both in maintaining cellular homeostasis, malignant hematopoietic cell expansion and the development of autoimmune disorders, including AIHA." (PMID 31803285, 2012). "The Fas receptor (Fas)-Fas ligand (FasL) apoptotic pathway participates in elimination of autoreactive B and T cells involved in molecular mimicry to maintain immune homeostasis; hence, this pathway may protect against autoimmune diseases such as GBS." (PMID 29432441, 2018). "In this prospective, we provide preclinical evidence that targeting Fas ligand (FasL) may provide a unique opportunity to prevent or cure T1D and perhaps other organ-specific autoimmune diseases without causing immune suppression." (PMID 22807927, 2012).